SYP (synaptophysin)
Description:
Possibly involved in structural functions as organizing other membrane components or in targeting the vesicles to the plasma membrane. Involved in the regulation of short-term and long-term synaptic plasticity (By similarity).
Synonyms: MRX96; MRXSYP; XLID96
Tractability: Antibody: UniProt predicts a signal peptide or a membrane-spanning region. PROTAC: UniProt records ubiquitination sites on it; its protein half-life has been measured.
Gene: Protein-coding gene on chromosome X (49,187,807 to 49,200,218, reverse strand). Ensembl gene ENSG00000102003.
Subcellular location: Cytoplasmic vesicle, secretory vesicle, synaptic vesicle membrane; Synapse, synaptosome
Pathways (Reactome):
Sensory Perception: Sensory processing of sound by inner hair cells of the cochlea
Gene Ontology:
Molecular function: cholesterol binding; protein binding; identical protein binding; SH2 domain binding
Biological process: endocytosis; regulation of long-term neuronal synaptic plasticity; regulation of neuronal synaptic plasticity; regulation of opioid receptor signaling pathway; regulation of short-term neuronal synaptic plasticity; synaptic vesicle maturation; synaptic vesicle membrane organization; modulation of chemical synaptic transmission; regulation of synaptic vesicle priming
Cellular component: neuron projection; presynaptic active zone; synaptic vesicle; synaptic vesicle membrane; excitatory synapse; membrane; neuromuscular junction; neuron projection terminus; perinuclear region of cytoplasm; presynapse; presynaptic membrane; Schaffer collateral - CA1 synapse; synapse; terminal bouton
Gene-disease validity (ClinGen):
ClinGen rates the evidence that SYP causes each of these diseases.
non-syndromic X-linked intellectual disability (X-linked): Moderate. Nonspecific X-linked intellectual deficiencies (MRX) belong to the family of sex-linked intellectual deficiencies (XLMR).
Homologues: Orthologues: chimpanzee SYP (99% identical), macaque SYP (97% identical), guinea pig SYP (95% identical), mouse Syp (95% identical), rat Syp (95% identical), pig SYP (91% identical), dog SYP (89% identical), zebrafish sypa (67% identical), zebrafish sypb (64% identical), Caenorhabditis elegans sph-1 (21% identical). Paralogues in human: SYNPR (55% identical), SYPL2 (38% identical), SYPL1 (33% identical).
Diseases named in the same sentence as SYP in open-access papers:
SYP is named in the same sentence as 341 diseases in open-access papers, as found by Europe PMC text mining. Sharing a sentence is not in itself a finding about the gene and the disease. The quoted sentences say what the papers report.
neuroendocrine tumors (135 papers, 2003 to 2026). "Recently, the marker INSM1 has been identified as another promising marker for neuroendocrine tumors, potentially improving diagnostic accuracy when combined with synaptophysin and chromogranin A." (PMID 40735045, 2025). "The intensity of synaptophysin expression is generally weaker than that of neuroendocrine tumors, and this is a limitation associated with its use in practice." (PMID 36401284, 2022). "In recent years, the reported incidence of neuroendocrine tumors has been increasing, probably due to the better sensitivity of diagnostic tests and more frequent staining of chromogranin A and synaptophysin during the histopathological examination." (PMID 34917031, 2021). "Immunohistochemistry showed synaptophysin positivity and chromogranin negativity, with a low mitotic index, suggestive of a neuroendocrine tumor." (PMID 42281724, 2026). "Neuroendocrine tumor cells contain chromogranin-A, synaptophysin, and neuron-specific enolase and can secrete hormones." (PMID 41281106, 2025). "According to the WHO neuroendocrine tumors of the thymus typically exhibit strong, diffuse immunoreactivity for at least one neuroendocrine marker, such as chromogranin A, synaptophysin, CD56, and neuron-specific enolase (NSE), in more than 50% of tumor cells." (PMID 40843719, 2025). "Cells are diffusely and strongly positive for chromogranin and synaptophysin with a Ki67 index of 3-4%, suggestive of intermediate-grade neuroendocrine tumor." (PMID 40291307, 2025). "The diagnosis of neuroendocrine tumors is characterized by the detection of immunohistochemical markers: synaptophysin, chromogranin A, and neuron-specific enolase." (PMID 39996224, 2025). "The liver biopsy confirmed a chromogranin +, synaptophysin +, Ki67 <2% well-differentiated neuroendocrine tumor; the small intestine was suggested as the primary site of the tumor." (PMID 39996224, 2025). "In these contexts, synaptophysin is used to differentiate neuronal and neuroendocrine tumors from purely glial tumors, highlighting its significance in CNS tumor classification." (PMID 40937216, 2025). "Among morphologically non‐neuroendocrine tumours, the number of cases showing positivity for at least two neuroendocrine markers was the same for synaptophysin/chromogranin A compared to synaptophysin/INSM1." (PMID 39526928, 2025). "For diagnosing a neuroendocrine neoplasm of the female gynecological tract, at least two positive neuroendocrine markers, such as synaptophysin, chromogranin, and CD56, are required." (PMID 41179607, 2025). "Beyond gliomas, synaptophysin is also expressed in neuroendocrine tumors, pheochromocytomas, paragangliomas, medulloblastomas, and central neurocytomas." (PMID 40937216, 2025). "The histopathological findings showed a well-differentiated neuroendocrine tumor with positive synaptophysin and chromogranin A immunostains." (PMID 38854200, 2024). "The neuroendocrine tumor was positive for chromogranin and synaptophysin; GIST showed immunopositivity for CD117 and SMA; Synovial sarcoma showed immunoexpression of panCK, Bcl2 and TLE1; and epithelioid angiomyolipoma was positive for vimentin, CK7 and HMB45." (PMID 38235567, 2024). "PGL and neuroendocrine tumors from different organs can share similarities in their nested structure and expression of neuroendocrine markers such as chromogranin A and synaptophysin." (PMID 39507200, 2024). "Immunohistochemical markers such as chromogranin A (CgA) and synaptophysin (Syn) are crucial for confirming neuroendocrine differentiation of tumors and are indispensable in the diagnosis of neuroendocrine tumors." (PMID 39507752, 2024). "Immunohistochemical positivity for neuroendocrine markers (synaptophysin and chromogranin) differentiates a neuroendocrine tumor and a mixed ductal-endocrine carcinoma." (PMID 39659325, 2024). "Immunohistochemical analysis revealed that the neuroendocrine tumor cells were positive for chromogranin A, synaptophysin, and CD56." (PMID 37306825, 2023).
neuroendocrine tumors (continued). "Within the dermis, a distinct infiltrative neuroendocrine neoplasm composed of sheets, nests, and cords of round basaloid cells was labeled with synaptophysin." (PMID 37774029, 2023). "The remaining specimen showed proliferation of epitheloid cells that were found by immunohistochemical analysis to be positive for chromogranin A and synaptophysin, consistent with a neuroendocrine neoplasm." (PMID 37306825, 2023). "Immunohistochemistry of the pancreatic lesion revealed CD56, synaptophysin, and chromogranin positivity, supporting the diagnosis of neuroendocrine tumor." (PMID 36936484, 2023). "Percutaneous biopsy of the liver mass demonstrated a well-differentiated neuroendocrine tumor (low grade) confirmed by immunohistochemistry with strongly positive chromogranin and synaptophysin stain." (PMID 37670372, 2023). "Subsequent immunohistochemistry analysis on these CDX tumors show positivity for commonly used markers for SCLC diagnosis: CD56, synaptophysin and chromogranin A, demonstrating the stability of the patient’s neuroendocrine tumor lineage." (PMID 36869231, 2023). "Neuroendocrine neoplasms are diagnosed by immunostaining, such as specific stains for synaptophysin, chromogranin A and INSM1." (PMID 37027114, 2023). "Further, a preoperative biopsy of the lesion revealed a small round cell tumor with positive immunostaining for ACTH and synaptophysin, suggestive of a neuroendocrine tumor." (PMID 37123777, 2023). "As a neuroendocrine tumor, neuroendocrine markers such as chromogranin A, synaptophysin, CD56, neuron‐specific enolase usually confirm the diagnosis." (PMID 36950672, 2023). "Neuroendocrine tumors are identified through immunohistochemical staining for common markers including chromogranin A/B, synaptophysin and neuron specific enolase (NSE)." (PMID 36440195, 2022). "Synaptophysin and other neuroendocrine tumor markers are also expressed in tumors unrelated to neuroendocrine cells." (PMID 36401284, 2022). "Both PDX tumors stained positive for the neuroendocrine tumor markers chromogranin A (CgA) and synaptophysin (SYP), but only the NEC913 PDX tumor stained positive for somatostatin receptor 2 (SSTR2)." (PMID 35454817, 2022). "Immunohistochemistry showed ALK, EMA, and AE1/AE3 immunoreactivity suggesting ALK-rearranged renal cell carcinoma (Case 1) and coexpression of keratin, EMA, synaptophysin, and chromogranin-A, suggesting neuroendocrine neoplasm (Case 2)." (PMID 34228212, 2022). "Histopathological examination of the samples revealed the presence of a probable neuroendocrine tumor (synaptophysin+, chromogranin+)." (PMID 33807230, 2021). "To validate synaptophysin as a tissue marker of NENs, we first stained neuroendocrine tumors of 54 patients." (PMID 34064565, 2021). "We also studied if WNT2 expression was associated with expression of enteroendocrine cell/neuroendocrine tumor markers chromogranin A (CHGA) and synaptophysin (SYP)." (PMID 34274970, 2021). "Traditional markers for neuroendocrine tumors comprise synaptophysin, chromogranin A, and CD56 (NCAM1)." (PMID 34884272, 2021). "This study describes the expression of synaptophysin on platelet surfaces of neuroendocrine neoplasms (NENs)." (PMID 34064565, 2021). "Meanwhile, TCACC is negative for neuroendocrine markers, such as chromogranin A and synaptophysin, and this immunohistochemical feature is useful in ruling out neuroendocrine tumors." (PMID 32756201, 2020). "Consistent with the fact that SCLC is a malignant neuroendocrine tumor of lung origin, the expanded CTCs were positively stained for neuroendocrine marker synaptophysin and lung tumor marker TTF-1." (PMID 33207745, 2020). "Chromogranin A (CgA), synaptophysin (Syn) and the Ki-67 index play significant roles in diagnosis or the evaluation of the proliferative activity of gastroenteropancreatic neuroendocrine neoplasms (GEP-NENs)." (PMID 32917216, 2020).
neuroendocrine tumors (continued). "Microscopy and immunohistochemistry uncovered a neuroendocrine tumor, staining positive for chromogranin A (CgA), synaptophysin and somatostatin, with a Ki67 = 1%." (PMID 32825782, 2020). "Pathological examination and immunohistochemical stainings such as chromogranin A, synaptophysin and Ki-67 are required for the diagnosis of a neuroendocrine neoplasm." (PMID 31731083, 2019). "Chromogranin A and synaptophysin expression is seen in 69.1 and 90.2%, respectively, of gastroenteropancreatic neuroendocrine neoplasms." (PMID 29740725, 2018). "To test for differentiation in AKT1 overexpressing cells, we performed immunohistochemistry for the differentiation marker Synaptophysin, which has been shown to be expressed in CNS tumors with neuronal differentiation as well as in neuroendocrine tumors." (PMID 29465400, 2018). "Neuroendocrine tumors (NETs) comprise a heterogeneous group of malignancies that express neuropeptides as synaptophysin, chromogranin A (CgA), and specific neuronal enolase (NSE), among others." (PMID 28194370, 2017). "Neural, neuroendocrine neoplasm, melanoma and Perivascular Epithelioid Cell Tumor (PEComa) were excluded because of negativity for S100, chromogranin, synaptophysin and HMB45." (PMID 27491291, 2016). "Neural, neuroendocrine neoplasm and melanoma and uterine Perivascular Epithelioid Cell Tumor (PEComa) were excluded because of negativity for S100, chromogranin, synaptophysin and HMB45." (PMID 27491291, 2016). "Neuroendocrine tumours (NETs) are a family of neoplasms that arise from neuroendocrine cells and express neural markers, such as synaptophysin or chromogranin A. They are mainly distributed in the gastrointestinal tract." (PMID 25933800, 2015). "Neuroendocrine tumours (NETs) are a family of neoplasms that come from neuroendocrine cells and express neural markers, such as synaptophysin or chromogranin A." (PMID 25933800, 2015). "Cytological examination of the aspirate from the solid component showed cohesive groups of plasmacytoid cells, staining positively for synaptophysin and chromogranin A, which are highly specific markers for neuroendocrine tumors." (PMID 25106541, 2014). "Neuroendocrine neoplasms are epithelial tumors with neuroendocrine differentiation, usually confirmed by positivity for neuroendocrine immunohistochemical markers such as synaptophysin and chromogranin." (PMID 25525544, 2014). "Cytological examination demonstrated cohesive groups of plasmacytoid cells staining positively for synaptophysin and chromogranin A, which is suggestive of a neuroendocrine tumor." (PMID 25106541, 2014). "They share uniform histological hallmarks, but in addition to morphology diagnosis of neuroendocrine tumors (NETs) is based on cell-specific markers that can be detected by immunohistochemistry (i.e., chromogranin-A and synaptophysin)." (PMID 24915894, 2014). "Differential diagnosis includes lymphomas, germ cell tumors, neuroendocrine tumors (as it shares some of the markers for neuroendocrine differentiation like synaptophysin and chromogranin), and primary lung malignancies." (PMID 25478263, 2014). "In the WHO classification neuroendocrine tumors have been defined as those in which one or more neuroendocrine markers, such as neuro specific enolase, chromogranin A, and/or synaptophysin, are expressed in at least 50% of cancer cells." (PMID 23734899, 2013). "Cytology specimens stained strongly positive for both synaptophysin and chromogranin, definitively making the diagnosis of neuroendocrine tumor." (PMID 22762002, 2012). "First, the lesion was initially diagnosed on EUS-FNA cytology as a well-differentiated neuroendocrine tumor (NET), illustrating a recognized diagnostic pitfall when SPNs show focal expression of neuroendocrine markers (e.g., synaptophysin, INSM1) and when material is limited." (PMID 41261629, 2025).
neuroendocrine tumors (continued). "Furthermore, immunohistochemical markers, such as neuron-specific enolase, chromogranin A, and synaptophysin, are used for their high sensitivity in the diagnosis of neuroendocrine tumors." (PMID 40141766, 2025). "With the help of immunohistochemistry, the histopathological finding of the specimen confirmed the diagnosis of multiple neuroendocrine tumors with positive expression of neuron-specific enolase, synaptophysin and chromogranin A. Subsequently, the patient received distal gastrectomy." (PMID 40406402, 2025). "Neuroendocrine tumors (NETs) of the small intestine, another important differential diagnosis, are typically chromogranin A and synaptophysin positive and may present with obstruction, anemia, or abdominal pain." (PMID 41302109, 2025). "GLI1-rearranged enteric tumors may show a focal-to-patchy expression of synaptophysin and CD56, which may pose a diagnostic pitfall by mimicking neuroendocrine tumors." (PMID 39851545, 2025). "Primary neuroendocrine neoplasms (NENs) of the breast are characterized by neuroendocrine architectural and cytological features, which must be supported by immunohistochemical positivity for neuroendocrine markers (such as Chromogranin and Synaptophysin)." (PMID 38980337, 2024). "Primary neuroendocrine neoplasms (NENs) of the breast are characterized by neuroendocrine architectural and cytological features, which must be supported by immunohistochemistry positivity for neuroendocrine markers (such as Chromogranin and Synaptophysin)." (PMID 38980337, 2024). "The results of the panel showed intense immunoexpression of S100 protein in the largest and superficial lesion, as well as positivity for chromogranin and synaptophysin in the minor and deep lesion confirming the diagnosis of rectal plexiform neurofibromas concomitant with neuroendocrine tumors." (PMID 36629684, 2023). "Furthermore, genes encoding canonical markers of neuroendocrine tumors—including CHGA (chromogranin A), SYP (synaptophysin), NCAM1 (CD56), and ENO2 (neuron-specific enolase)—were all differentially higher in s3 tumors." (PMID 36731467, 2023). "The combination of hematoxylin and eosin staining, Ki-67, and immunostaining of classic neuroendocrine markers, such as chromogranin A, CD56, and synaptophysin, are normally used to diagnose high-grade neuroendocrine tumors; however, they are frequently heterogeneous." (PMID 34829292, 2021). "Until 2003, a breast cancer could be classified as a primary neuroendocrine tumor when expressing chromogranin A, chromogranin B, or synaptophysin in more than 50% of the total cell population." (PMID 33584543, 2020). "For neuroendocrine tumours, the panel should include synaptophysin, chromogranin A, and CD56." (PMID 29808414, 2018). "In the present study, the results of the microscopic examination were consistent with the features of a neuroendocrine neoplasm, and the immunohistochemical staining was positive for glucagon, synaptophysin and chromogranin A. These findings confirmed the diagnosis of a glucagonoma." (PMID 25789004, 2015). "In this study, we investigated whether NPS or NPSR1 might be used as biomarker for NET in a wide panel of neuroendocrine tumors, characterized by assessing the Ki-67 proliferation index and chromogranin-A and synaptophysin expression." (PMID 24915894, 2014). "Tumorspheres derived from pRb-negative tumors do not express pRb and express the neuroendocrine tumor markers synaptophysin and microtubule-associated protein 2 (MAP2)." (PMID 23826078, 2013). "Neuroendocrine tumors are supposed to be of neuroectodermal origin and possess properties typical of neuroendocrine cells, like containing secretory granules, producing neuroendocrine factors including chromogranin, synaptophysin and specific hormones." (PMID 22253802, 2012).